CRP (C-reactive protein)
Diseases named in the same sentence as CRP in open-access papers (continued):
Sharing a sentence is not in itself a finding about the gene and the disease.
depression (continued). "Finally, increased inflammatory markers that are common in arthritis, such as C-reactive protein or nitric oxide are also more common in individuals with depression than those without." (PMID 32395714, 2020). "In addition, several cases of major depressive disorders and anxiety disorders do not response to conventional antidepressants, in patients with a serum CRP level > 3 mg/L." (PMID 32503468, 2020). "However, it should be noted that enhanced CRP levels are not specific to depression—they are also present in euthymic BPD and manic episodes." (PMID 33255237, 2020). "In the omalizumab group, there was also a very significant reduction in the levels of UAS7 (p < 0.001) and a significant reduction in the Anxiety Scale, ESR and DLQI (p < 0.01) after therapy, but no significant decrease in the depression scale and CRP (p > 0.05)." (PMID 33235810, 2020). "Moreover, the MI+ depression model also exhibited similar results to those of the IM group in terms of echocardiography (EF and FS), cardiac markers (CK-MB and LDH), antioxidants (SOD, GSH-Px, and CAT) and inflammatory factors (CRP, IL-6, and TNF-α)." (PMID 32973539, 2020). "The primary aim of this analysis was to explore whether proposed physical and psychological function measures (depression, anxiety, fatigue, and physical functioning) and mechanistic biomarkers (BDNF, HOMA2-IR, and CRP) mediated intervention effects on cognition." (PMID 31605514, 2019). "Among men without depression, those with higher levels of inflammation (CRP > 0.2 mg/dL) had increased odds of having shortened telomere length compared to those in men with lower levels of inflammation (CRP ≤ 0.2 mg/dL)." (PMID 31109116, 2019). "Some of the inflammatory markers are considered as to be (potentially) significant for depression, e.g., the pro-inflammatory cytokines as interleukin-6 (IL-6), interleukin-1 (IL-1), and tumor necrosis factor (TNF-α), as well as the acute phase reactant protein C-reactive protein (CRP)." (PMID 31591316, 2019). "Unadjusted and adjusted linear and logistic regression models were used to assess the relationship between the tertiles of CRP concentration and the telomere length stratified by the status of depression such as major depression or depressed affect vs. no depression." (PMID 31109116, 2019). "It is important in the context of the observed gender-toxoplasmosis-bartonellosis interaction that the negative correlation between the inflammation marker CRP (C-reactive protein) and depression was also reported to exist in men, but not in women; for a survey and discussion see." (PMID 30061846, 2018). "Indeed, increased rates of peripheral inflammation, notably interleukin (IL)-6 and CRP, appear to differentiate MS patients suffering from comorbid depression from those who do not." (PMID 29294244, 2018). "Interestingly, other commonly used indicators of disease activity, such as C-reactive protein levels or Sedimentation Rate, do not correlate with depression." (PMID 29659589, 2018). "However, we only tested one marker of inflammation (CRP) because other robust markers of inflammation (e.g., IL-6 and TNF-α) are not available in the NHANES data set, and the current utility of these inflammatory markers in depression is unclear." (PMID 30524737, 2018). "Similarly, CRP levels are not expected to be changed following both treatments in the ‘Depression with no inflammation’ stratum." (PMID 30126458, 2018). "Whilst a small number of these studies assessed depression symptoms, none examined the effect of these symptoms on the relationship between CRP and cognition; thus, the extent to which this relationship might be explained by psychiatric morbidity is unknown." (PMID 28694011, 2017). "In addition, when total depression was categorized as somatic symptoms and non-somatic symptoms, the depression-CRP relationship remained significant, suggesting that the inflammation-depression relationship cannot be changed by different depressive subtypes." (PMID 28128231, 2017).
depression (continued). "In OSA and major depression, there are arguments in favour of chronic inflammation, which may be correlated with the severity of OSA and which may result in higher plasma levels of CRP and ferritin." (PMID 29202829, 2017). "In the Whitehall II study, for example, high levels of CRP and IL-6 at baseline have been associated with an increased risk of future cognitive symptoms of depression whereas baseline symptoms of depression did not predict the level of CRP or IL-6 at follow-up." (PMID 26631274, 2016). "Interestingly, the baseline Beck Depression Inventory-II scores correlated positively with changes in IL-6 levels over the follow-up period, but not with changes in CRP levels." (PMID 27918465, 2016). "The majority of major depressive patients included in our meta-analysis could be classified as severely or very severely depressed; IL-6, CRP and TNF-α were more strongly associated with severe than non-severe forms of depression." (PMID 26065825, 2015). "Furthermore, baseline CRP and IL-6 measurements have been observed to effectively predict future depression at 12-year follow-up, while baseline symptoms of depression were not predictive of future inflammatory markers." (PMID 26550011, 2015). "The lack of consensus with regard to CRP and development of depression may in part be due to the high biological variation of CRP (hsCRP)." (PMID 25329298, 2014). "In the unadjusted analyses severity of sleep disturbances increased with female sex, low socioeconomic status, living without a partnership, cardiovascular disease, depression, anxiety, poor physical health, increased levels of C-reactive protein and fibrinogen." (PMID 25093413, 2014). "In addition, vascular risk factors, including high body mass index level, presence of inflammation markers (e.g., CRP, TNF-α, Hs-CRP, and IL-6), and lack of physical activity, were associated with depression." (PMID 24752391, 2014). "In a recent review of the connection between depression and inflammation, Krishnadas pointed out that a third of patients with major depressive disorder (MDD), without any other major illness, have elevated inflammatory biomarkers; in particular, CRP, TNF-α, and IL-6." (PMID 23898306, 2013). "Overall, the positive association observed in the current study between continuous CRP levels and depressive symptoms in African American men is consistent with the findings of a meta-analysis, which reported that CRP and depression were significantly related in men, but not women." (PMID 24151548, 2013). "In addition, individuals with diabetes and MDD were found to have significantly higher CRP levels than non-diabetic patients with depression." (PMID 24109426, 2013). "Some studies have shown that following SSRI treatment for major depression, there was a significant drop in C-reactive protein (CRP) concentrations, irrespective of whether or not the depression resolves." (PMID 21701640, 2011). "Selective serotonin reuptake inhibitor (SSRI) therapy in subjects with depressive disorder significantly decreased CRP levels whether or not the depressive condition was resolved." (PMID 20617007, 2010). "Notably, previous studies as well as our data suggest that levels of CRP are higher during an ongoing depression than after recovery, hence suggesting CRP to be a state dependent rather than a trait dependent marker of depression." (PMID 18384670, 2008). "In these patients, C-reactive protein dropped significantly after treatment, independent of whether depression resolved." (PMID 17397549, 2007). "We have previously identified an association between GHQ-12 and the inflammatory marker C-reactive protein (CRP) in users of antidepressants but not non-users in Understanding Society, consistent with the well-established notion of an inflammatory, treatment-resistant subtype of depression." (PMID 39911945, 2025).
depression (continued). "A relevant role of sex hormones was hypothesized to sustain this disparity, and, interestingly, men with depression were found to present with lower testosterone (not exhibiting anti-inflammatory properties) and higher CRP levels compared to male healthy controls." (PMID 40305313, 2025). "Furthermore, growing evidence suggests that individuals with depression also exhibit elevated levels of circulating cytokines like IL-6, IL-1β, TNF-α, IFN-α, prostaglandin E2 (PGE2), and chemokine CCL2, as well as acute-phase proteins such as C-reactive protein (CRP)." (PMID 40573262, 2025). "Being female, having DM and experiencing depression were all associated with higher CRP, while carrying APOE E4 was associated with lower CRP in both univariate and multivariate GLM (all p< 0.001) in all populations (all participants with/without DM and DM patients with/without DR or depression)." (PMID 40778276, 2025). "However, one recent RCT found increases in anti-inflammatory markers in the physical activity conditions relative to other groups as well as reductions in depression symptoms, though CRP was not reduced outside of a subgroup analysis of patients with potentially higher cardiovascular risk." (PMID 41661985, 2025). "Consequently, studies on a broader range of immune markers (e.g. cytokines, immune cells) and specific immune pathways would be more useful to understand the role of inflammation in depression, rather than CRP which is a non-specific marker of systemic immune activation." (PMID 38699368, 2024). "Moreover, many inflammatory signaling pathways (i.e., IL-1–6, IL-23, and CRP) depend on a parasympathetic and hypothalamus–pituitary–adrenal (HPA) axis dysregulation, which has been proven to participate in triggering mental disorders, including depression, schizophrenia, and bipolar disorders." (PMID 37109640, 2023). "Furthermore, in an animal model of treatment-refractory depression with chronic administration of adrenocorticotropic hormone (ACTH), animals that responded to ketamine exhibited higher baseline plasma concentrations of C-reactive protein (CRP) and tumoral necrosis factor-α (TNF-α)." (PMID 36970275, 2023). "Similarly, four-year later depression was not related to four-year later CRP (r = 0.03, p = 0.07)." (PMID 36860788, 2023). "A case-control study explored CRP levels in MDD subjects and its phenotypic associations in 102 TRD patients who currently experience depression, 48 treatment-responsive patients not undergoing depression, 48 patients not receiving medication, and 54 healthy volunteers." (PMID 35163538, 2022). "Further, there could also be other potential confounders for the relationship between pain and CRP that were not considered within this analysis such as psychological factors (e.g., depression, anxiety, stress, early life adverse events) and socioeconomic factors." (PMID 36411323, 2022). "A few research groups have worked under this hypothesis, and the results of their studies in younger adults found that exposure to MBCT resulted in a significant reduction in EGF but not in the levels of circulating IL-8 and CRP in subjects with depression and anxiety when compared to controls." (PMID 35002817, 2021). "Thus, CRP level is no moderator of the relationship between vitamin D and depression." (PMID 34201276, 2021). "However, inflammation is likely to be relevant for some, not all, cases of depression or psychosis, as meta-analyses have reported that evidence of inflammation, e.g., elevated CRP levels (>3 mg/L), are present in about a quarter of patients with depression or psychosis." (PMID 33684738, 2021). "However, the proof of concept that CRP levels at baseline might be indicative of treatment response to anti-inflammatory treatments in depression has not been studied prospectively yet." (PMID 30126458, 2018). "However, abuse and depression did not interact to predict CRP at two time points." (PMID 30127754, 2018).
depression (continued). "However, compared to those without depression, individuals with depression had significantly higher CRP levels (4.1(1.9-7.6) vs 1.5(0.5-4.4) mg/l; p = 0.02; Mann Whitney test) and 24-hour urine free cortisol (71.4 ± 21.3 vs 59.8 ± 29.3 ug/24 h; p = 0.03; Mann Whitney test)." (PMID 23410093, 2013). "Thus, our results do not support the depression-inflammation hypothesis with respect to the biomarkers assessed (CRP, IL-18, IL-1-ra, albumin, fibrinogen)." (PMID 23967272, 2013). "In addition, cerebral atherosclerotic changes may result in cognitive impairment and depression, possibly mediated by C-reactive protein but results were not consistent." (PMID 22784860, 2012). "It has been observed that C-reactive protein (CRP) and erythrocyte sedimentation rate (ESR) levels were higher in a group of patients suffering from psoriasis and depression than in psoriatic patients without depression." (PMID 40141110, 2025). "Study has suggested that individuals with depression generally display higher levels of interleukin-1 (IL-1), IL-6, TNF-α, and CRP compared to non-depressed individuals." (PMID 40313907, 2025). "Markers of inflammation, such as C-reactive protein (CRP), IL-12, are significantly elevated in patients with depression compared to those without depression, even after accounting for confounding factors." (PMID 40002741, 2025). "Three studies reported significant differences in inflammatory protein concentrations between MS participants with and without depression for IL-6 in serum, and IL-9,30 TNF-α and CRP in both serum and CSF." (PMID 39867847, 2025). "Comparison depression, POAG, AD, APOE E4 status and level of CRP in patients with and without DM or DR and in female and male patients with DM or DR." (PMID 40778276, 2025). "In our study, both CRP and ESR show higher values in all three evaluations in patients with depression compared to those without depression, with statistical significance for ESR." (PMID 38610822, 2024). "Higher levels of pro-inflammatory markers such as CRP, IL-6 and TNF-α and more fatigue are seen in patients with depressive disorders because of negative effects on the nervous system." (PMID 38297218, 2024). "Plasma concentrations of stress and inflammatory biomarkers (cortisol, CRP, IL-6 and TNF-α) have been found to be increased in patients with major depressive disorder who have a history of treatment non-response, compared to treatment-responsive patients." (PMID 36648973, 2023). "One study showed a positive relationship between CRP levels in COPD patients and depression when compared to patients without depression." (PMID 36960961, 2023). "This was most notable in subjects who experienced a clinically significant improvement in depression where they had significant decreases in IL‐6, CRP, and tumor necrosis factor alpha (TNF‐α) compared to those who experienced no improvement in depression." (PMID 36178333, 2023). "Linear models were compared between all exposures of interest and two outcomes, a binary (yes/no) lifetime depression measure (MDD) and a continuous log-transformed circulating CRP measure." (PMID 36712567, 2023). "We found that taking NAC for 12 weeks by people under MMT improved depression and anxiety symptoms, HOMA‐IR, and levels of hs‐CRP, GSH, and TAC concentrations; however, it did not have any effects on sleep quality, and other biochemical parameters." (PMID 36448959, 2023). "Only one study demonstrated a statistically significant mediating role of CRP between DII and depression in 10,022 adults aged 20 years and older, but it was not considered to be substantial or clinically significant because of the minimal mediating effect." (PMID 36615742, 2022). "In fact, these studies saw significant correlations between depression and other inflammatory markers such as IL-6 and TNF-α, but not CRP." (PMID 35618889, 2022).
depression (continued). "Furthermore, it would appear that there is a subgroup of depressed patients who showed a low-grade inflammatory state (i.e., CRP > 3.0 mg/L), corroborating the hypothesis that inflammation might contribute to developing some types of depression, but not all of them." (PMID 35163538, 2022). "A considerable body of evidence suggests that individuals with diagnosed depression exhibit significantly higher levels of IL-1, IL-6, TNF-α, and C-reactive protein (CRP) compared to non-depressed counterparts." (PMID 31068783, 2019). "Our results agree with this finding as depression, as measured by the CESD score, was related to both hs-CRP and CSM score (result not shown)." (PMID 30367094, 2018). "In this meta-analysis, we found that elderly with depression had significantly higher peripheral levels of IL-1β (p = 0.026), IL-6 (p < 0.001) but not TNF-α (p = 0.351) and CRP (p = 0.05)." (PMID 30104698, 2018). "Even though there are studies showing that people with depression have elevated levels of inflammatory biomarkers, such as TNF-alpha, IL-6, and CRP, inflammation is not necessary or sufficient for the diagnosis of depression." (PMID 26451727, 2015). "The SWAN study of 3292 pre- and postmenopausal women found that over a five-year observation period, higher depression scores were related to higher levels of fibrinogen and plasminogen activation inhibitor type one (PAI-1) but not CRP." (PMID 25329298, 2014). "We found significant correlations between fatigue, depression and anxiety on one hand, and TNF-α and sIL-2R, but not CRP or IL-6, on the other hand." (PMID 23082161, 2012). "Previous studies have suggested that higher levels of several proinflammatory biomarkers such as C-reactive protein, IL-6 and TNF-α may be related to non-response to antidepressant drugs in people with major depressive disorder." (PMID 40624224, 2025). "Other proinflammatory factors, including high-sensitivity CRP and IL-1, increased significantly in patients with TD, compared with T2DM patients without depression, and depression scores were positively correlated with vascular endothelial growth factor, IL-1b, and MCP-1, respectively." (PMID 37213540, 2023). "However, there was evidence for an association of a genetically-predicted effect of IL-6 activity on CRP levels with smoking (ORIL-6/CRP–Smk = 1.06 (1.03–1.09), p < 0.001, but not depression (ORIL–6/CRP-Dep = 0.93 (0.85–1.02), p = 0.126." (PMID 36057695, 2022). "No mediation effect of CRP was found between DII and any of our depression outcome measures." (PMID 35565951, 2022). "In support of this concept of heterogeneity in MDD, a recent study found distinct immunologic profiles for inflamed and non-inflamed depression, with the inflamed group characterized by increased levels of circulating neutrophils, monocytes, CD4+ T cells along with elevated IL-6 and CRP." (PMID 35332134, 2022). "White blood cell count or albumin level were not significantly different between the two groups (p = 0.2346, 0.0662, respectively), while inflammatory markers including CRP (p = 0.0190) and ESR (p = 0.0245) were higher in CD patients with symptoms of anxiety/depression versus those without." (PMID 33446900, 2021). "Moreover, other inflammatory markers that were found to be relevantly involved in depression such as IL-1 and TNF-α were not available from the LIFE-Adult-Study; for this reason, only IL-6, CRP and WBC were examined in this work." (PMID 34201276, 2021). "In general, TRD and drug-free patients had similarly increased levels of inflammation-related genes: this applied to both the genes that had been measured before in depression (IL1-beta, IL-6, TNF-alpha and MIF) and those never measured before (A2M, CRP, P2RX7, CCL2 and STAT1)." (PMID 32699209, 2020). "With regard to CRP, the findings of two studies were consistent: there were no significant changes in the levels of CRP or hsCRP from baseline to post-intervention in patients with MDD or with depression or anxiety." (PMID 32260096, 2020).